CD28 (CD28 molecule)
Diseases named in the same sentence as CD28 in open-access papers (continued):
Sharing a sentence is not in itself a finding about the gene and the disease.
lung cancer (41 papers, 2014 to 2026). A malignant neoplasm involving the lung. "We discovered that levels of NK cells, CD4+ T cells, naïve CD4+/CD4+, naïve CD4+ T cells, CD4+CD28+ T cells were significantly different in lung cancer patients versus healthy individuals and that the percentages of the different cell subsets are associated with lung cancer stage." (PMID 34488711, 2021). "Studies in lung cancer have shown that CD8+CD28+PD1− T cells exhibit a more naive phenotype, although research on this T cell subset in relation to tumors is currently limited." (PMID 40136325, 2025). "Conversely, increased CD28 expression correlates with longer OS, indicating different effects on lung cancer prognosis." (PMID 39684559, 2024). "PD-1+CD8+ T cells that proliferate in the peripheral blood of lung cancer patients receiving PD-1 therapy express CD28, CD38 and HLA-DR." (PMID 37881432, 2023). "Secondly, the CD28/B7 pathway plays an important role in the proliferation of CD8+T cells after PD-1 blockade therapy in lung cancer patients." (PMID 35484541, 2022). "It has been recently demonstrated that B7-1, B7-2 and CD28 co-stimulation is necessary to revive exhausted T cells using anti-PD-1 therapy in animal models and lung cancer patients." (PMID 33014820, 2020). "Both LUAD and lung cancer patients with high CD28 expression had shorter disease-free survival (DFS) (P = 0.0011; P = 0.0001) but longer overall survival (OS) (P = 0.0001; P = 0.0282)." (PMID 32967633, 2020). "In this study, we confirmed the important role of CD28 in the prognosis of lung cancer, especially in young patients with LUAD." (PMID 32967633, 2020). "The expression of CD28 has also been related to the assessment of the prognosis of lung cancer." (PMID 39684559, 2024). "Notably, these signatures were highly represented in advanced lung cancer patients responding to atezolizumab, only in the presence of CD28." (PMID 37898752, 2023). "Lung cancer patients who responded to PD-1 therapy had more CD28+T cells, suggesting that CD28 may predict treatment response." (PMID 36389699, 2022). "We suppose that high CD28 expression may be due to CD4+ T-cell activation related to micrometastases in LNs in lung cancer patients and may control the metastatic cells in these compartments." (PMID 32808188, 2021). "Anti-PD-1 therapy in lung cancer patients shows upregulation of CD8+ CD28+ PD-1+ T-cells in blood." (PMID 32575351, 2020). "Therefore, high CD28 expression suppresses the adaptive immune response to cancerous cells and acts as a tumorigenic factor in the early stage of lung cancer development, which is related to the rapid progression of the disease." (PMID 32967633, 2020). "CD28, which is associated with poor DFS but long OS, might serve as a novel biomarker for the prognosis of lung cancer, and the different effects of CD28 on lung cancer prognosis should be considered." (PMID 32967633, 2020). "However, high levels of CD28 expression were related to longer OS, which suggested the different effects of CD28 on the prognosis of lung cancer." (PMID 32967633, 2020). "In lung cancer, CD28−PD1+ and CD28−PD1− T cells displayed enhanced secretory capabilities for granzyme B, IFN-γ, and TNF-α, whereas CD28+PD1− and CD28+PD1+ T cells exhibited diminished secretory functions, consistent with our findings." (PMID 40136325, 2025). "In patients with lung cancer, CD8+CD28− T cells have elevated Foxp3 expression and show immunomodulatory effects." (PMID 34259422, 2021). "We found that CD122 and CD279 increased and CD28 and CD183 decreased in the patients with lung cancer (n = 4) compared to that in healthy volunteers (n = 3, whereas N2 was excluded sine PD1 highly expressed) (all p < 0.05)." (PMID 34680466, 2021). "Novel bio-nanocarriers composed of magnetic nanoparticles and fucoidan-dextran (IO- FuDex3) conjugated to T-cell activators (anti-CD28 and anti-CD3) or checkpoint inhibitors (anti-PD-L1) were developed and evaluated for their efficacy in lung cancer." (PMID 34138386, 2021).
lung cancer (continued). "Therefore, CD28 might serve as a regulator in the TIME of lung cancer." (PMID 32967633, 2020). "Similar accumulations of CD28− and CD57+ cells have been observed within the CD8+ T cell pool in patients with lung cancer." (PMID 28751932, 2017). "Our results suggest that the NKG2D/CD28 CCR, when combined with a CAR, could enhance immune therapy outcomes for malignant tumors such as B-cell lymphoma and lung cancer." (PMID 40181405, 2025). "Interestingly, a reduction of CD28+CD57-CD8+ and an increase of CD28-CD57+CD8+ T cells has been observed in patients with advanced lung cancer, accounting for a reduced proliferative capacity and dysfunctional antitumor activity." (PMID 36902620, 2023). "Furthermore, immunofluorescence showed the ability of TIM-3-ECD to bind to the surface of lung cancer A549 cells and to provide an additional boost for the expression of the lymphocyte activation marker CD69 in anti-CD3/CD28 activated human PBMC." (PMID 37588136, 2023). "The previous study had shown that when elongating two second-generation CD28/4-1BB/CD3ζ CARs by a DAP10 domain, these CAR-T cells showed superior antitumor activity against other cancers, such as gastric cancer, lung cancer, and hepatocellular carcinoma, in xenograft-bearing mice." (PMID 34868314, 2021). "Tregs were isolated from lung cancer patient PBs and cultured with CD3/CD28 dynabeads for 48 h." (PMID 28261204, 2017). "Consequently, targeted Cd28 silencing reshapes the immunosuppressive tumor microenvironment, augmenting twofold CD8+ T cell infiltration and dendritic cell activation to extend survival in murine breast and lung cancer models to 1.3-1.5 folds." (PMID 42261788, 2026). "Firstly, patients with lung cancer treated with PD-1 inhibitors have a highly specific subset of proliferating CD8+ T cells in the peripheral blood, expressing effector-like phenotypes (HLA-DR+, CD38+, Bcl-2lo), costimulatory molecules (CD28, CD27, ICOS), and high levels of PD-1." (PMID 35484541, 2022). "Indeed, studies have reported incremental changes to biomarkers of immunosenescence following repeated administration of chemotherapy, including lower ratios of CD4+ T cells to CD8+ T cells and accumulations of CD28− and CD57+ cells in patients with breast and lung cancer." (PMID 28751932, 2017).
leukemia (37 papers, 2008 to 2025). A malignant (clonal) hematologic disorder, involving hematopoietic stem cells and characterized by the presence of primitive or atypical myeloid or lymphoid cells in the bone marrow and the blood. "The association between CTLA-4, ICOS, and CD28 polymorphisms and leukemia risk were assessed among Iranian patients." (PMID 32375828, 2020). "Although CD19.CD28 CAR-T cells were initially better at killing NALM6 leukemia, 79.9% of mice eventually relapsed." (PMID 40568128, 2025). "In the CD2-Lmo2 transgenic (Lmo2Tg) model of ETP-ALL, leukemia arises from an expanded CD4-CD8-CD44-CD25+CD28- (DN3a) thymocyte population, which contains preLSCs that display a stem-like phenotype." (PMID 39849166, 2025). "T cells expressing a CAR containing a distal IL7Rα domain (CD28.IL7R.ζ) had superior leukemia control in vivo when compared with the T cells expressing a CAR with a proximal IL7Rα domain (IL7R.CD28.ζ) and with CAR-T cells secreting IL7." (PMID 39186002, 2024). "Compared with control cells (CD28Con), CD28 silencing significantly inhibited cell growth, especially in Jurkat cells, indicating a potential leukemia-promoting role of CD28 in T-ALL cells." (PMID 38233409, 2024). "Intriguingly, larger amount of CD28-TGITI+CD8+ T cells at diagnosis was associated with poor treatment response and shorter leukemia free survival." (PMID 36960073, 2023). "They showed that CAR-T cells incorporating CD28.CD3ζ and infused at low doses (1x105 - 2x105) produced significantly higher tumoricidal effects against leukemia development than CAR-T cells with 4-1BB.CD3ζ co-stimulation." (PMID 36817460, 2023). "Accordingly, CAR T cells with a CD28 hinge displayed superior cytotoxicity against CD19low leukemia cells in vitro and in a mouse model compared with CD8α hinge CAR T cells." (PMID 38090558, 2023). "CD3/CD28 bead-expanded T cells that had been transferred with the CAR RNA or Blina-RNA partially controlled leukemia at similar levels." (PMID 27258611, 2016). "Our finding that CD28 is a direct target of Notch signalling is of interest both in terms of T cells development and leukaemia, and also in mature T cell activation." (PMID 19508709, 2009). "Similarly, in leukemias such as B-ALL, polymorphisms in genes such as CD28 have also been linked to the intensity of CRS in patients receiving CAR-T cell therapy, an immunotherapeutic modality." (PMID 40004863, 2025). "Since BACH2OE xenografts showed low leukemia burden in the BM, we then wondered whether these events are mediated by reduced CD28 and/or CD40LG levels in T-ALL cells upon BACH2 overexpression." (PMID 38233409, 2024). "In France, Garnache-Ottou and team investigated the anti-leukemia efficacy and safety of a third generation lentiviral CD28/4-1BB CAR-T cell product targeting CD123 (CAR123), and provided strong preclinical rationale for the clinical assessment of this autologous cell therapy." (PMID 35565416, 2022). "In our previous report comparing CD3/CD28 Dynabead T cells with OKT3/IL-2 T cells in the Nalm6 leukemia mouse model, the mice were treated with CD19 CAR RNA-electroporated T cells, and we found that OKT3/IL-2 T cells were inferior to the CD3/CD28 Dynabead T cells in controlling leukemia." (PMID 28523432, 2017). "Significantly however, we find that, upon repeated exposure to antigen and adoptive transfer to tumor-bearing mice, 19-28z-CAR transduced human T cells display enhanced expansion and greater in vivo anti-leukemia efficiency than CD19-targeted T cells that are costimulated through CD28/CD80." (PMID 26110267, 2015). "However, pretreatment with chidamide but not decitabine significantly inhibited the proliferation of both CD4+ and CD8+ T cells activated by anti-CD3 and anti-CD28 mAbs, suggesting a possible inhibition of anti-leukemia T cell immunity by chidamide in vivo." (PMID 23940586, 2013).
leukemia (continued). "The Sadelain group extensively compared CD28.CD3ζ and 4-1BB.CD3ζ co-stimulation designs in stress tests using the CD19CAR-T cells in the Nalm-6 leukemia xenograft model." (PMID 36817460, 2023). "CD28-mediated costimulation was very important in T-cell activation; CD4+CD28+ T cells and CD8+CD28+ T cells mediated graft-versus-leukemia (GVL) effect to prevent relapse, and CD4+CD28+ T cells also mediated protection against infections." (PMID 35936697, 2022). "Next, we determined the ability of splenic Tregs population, sorted from control and TCL1 leukemia-bearing B6 FoxP3EGFP mice to inhibit CD8+ T cell proliferation in an antigen unspecific test, where T cells were activated via anti-CD3 and anti-CD28 antibodies." (PMID 35296093, 2022). "Identical findings were obtained with a number of EL4 sublines and B cell and pre-B cell leukaemia cell lines that carry infectious viruses, and with uninfected primary naïve and CD3/CD28-simulated T cells and primary naïve and LPS-stimulated B cells." (PMID 32453763, 2020). "In our previous work in a xenograft model of leukemia, we compared two T cell manufacturing methods that are commonly used in adoptive immunotherapy clinical trials, CD3/CD28 Dynabead and OKT3/IL-2." (PMID 28523432, 2017). "After stimulation by CD19 positive leukemia lines, the CD3/CD28 Dynabead T cells and OKT3/IL-2 T cells secreted similar amounts of IFN-gamma." (PMID 28523432, 2017). "Next, we asked whether activation of CD28- and/or CD40LG-mediated signaling reverses BACH2OE-induced low leukemia burden." (PMID 38233409, 2024). "It is not clear, whether the conclusion also holds for CD28 costimulated CAR T cells as canonical CD28 CAR T cells display higher IL-2 production and tumor control in response to CD19low leukemia compared to 4-1BB-costimulated ζζ CAR T cells." (PMID 38090558, 2023). "Finally, incorporating 41BB signaling into CD28-CARs using in trans design enhances therapeutic efficacy and persistence of CAR T-cells in leukemia and solid tumor models." (PMID 37333156, 2023). "It is notable that using either the 4-1BB or CD28 costimulatory domain in the context of the CD28 hinge and transmembrane domain resulted in CAR-Ts that had equivalent anti-tumor activity in an in vivo model of a CD19-low expressing leukemia." (PMID 37518011, 2023). "Finally, altered expressions of CD28, CCR7, CX3CR1, IFNG, LTB and PRF1 were all contributing to the inflammatory profile of the TCRγδ+ T-LGL leukemias." (PMID 28407008, 2017). "Here, we lentiviral-transduced the same CD19 CAR into Dynabead T cells, OKT3-28BB-86BBL RNA-T cells, and OKT3/IL-2 T cells and tested their anti-leukemia activity in the Nalm6 model, and the OKT3/IL-2 T cells were still inferior to the CD3/CD28 Dynabead T cells in controlling leukemia." (PMID 28523432, 2017). "Having established that activation of CD28 enhances the activity of AMG 330 in leukemic cell lines, we aimed to assess whether activation of CD28 also impacted the efficacy of BiTE antibody constructs against primary patient leukemia cells." (PMID 26295610, 2015).
influenza (36 papers, 2010 to 2025). An acute viral infection of the respiratory tract, occurring in isolated cases, in epidemics, or in pandemics; it is caused by serologically different strains of viruses (influenzaviruses) designated A, B, and C, has a 3-day incubation period, and usually lasts for 3 to 10 days. "Higher senescent CD8 + CD28- T-cells have been associated with advancing age, influenza vaccine failure and CMV infection." (PMID 24742120, 2014). "We observed that the percentage of Tfh cells that had lost CD28 expression decreased over time during the response to influenza, suggesting that Tfh maintenance is impaired by the loss of CD28." (PMID 25347065, 2014). "Additionally, impaired influenza vaccine responses are associated with expanded CD8+ CD28- memory T cell populations and reductions in CD4+ T follicular helper cells (TFH) in older adults." (PMID 36650551, 2023). "The poor responsiveness to influenza vaccination has been shown to be specifically associated with the presence of high proportions of a population of inactive CD8+T lymphocytes that lack expression of the co-stimulatory molecule CD28." (PMID 27580076, 2016). "Moreover, Xie and McElhaney reported that susceptibility to influenza infection in older adults is associated with an increase in the number of CD8+CD28- T cells." (PMID 23675689, 2013). "The influenza-specific CD4+T cells were primarily of memory phenotype (CD28+CD45RA− or CD28null), with a significantly higher frequency than the cit-TNC-specific cells (p<0.05 in both groups)." (PMID 39557489, 2024). "As expected with CMV-based vectors, CyCMV/Flu-elicited CD4+ and CD8 + T cells recognizing influenza antigens exhibited a predominantly TEM phenotype in peripheral blood as measured by expression of CD28 and CCR7." (PMID 39030218, 2024). "The costimulatory pathway CD28 signaling is essential for activating helper T cells and protective immunity to influenza infection." (PMID 36059479, 2022). "The increase in the absolute numbers of lung ILC1s correlated with an increased expression of TRAIL, CD49a, and CD28 in mice treated with αGalCerMPEG prior to influenza infection." (PMID 31440243, 2019). "Sustained signaling from CD28 is critical for Tfh survival as evidence from apoptosis of Tfh cells during influenza viral or Citrobacter rodentium infection into a mice strain that after initial priming selectively lose CD28 expression on CD4 T cells." (PMID 27933060, 2016). "Consistent with this, there was an increase in the number of apoptotic Tfh cells 14 days after influenza infection in Cd28flox/floxOx40cre/+ mice compared with heterozygous controls, and this was most pronounced in the cells that had lost CD28 expression." (PMID 25347065, 2014). "Expression of CD28 on Tfh in the medLN and Th1 cells in the lung was determined 12 days following influenza infection: 30–40% of Tfh cells and 55–65% of lung Th1 cells had lost CD28 expression in Cd28flox/floxOx40cre/+ mice." (PMID 25347065, 2014). "We found that influenza-specific CD8 T-cells express similar levels of CD28 before and after infection with SIV." (PMID 22403659, 2012). "In severe influenza CD8 activation peaked more than 9 days post-onset, and/or was excessive (30–90% HLADR+CD38+) in association with accumulation of CD27+CD28− cells and maintenance of CD8 counts." (PMID 22363665, 2012). "Together, our results show influenza-derived GFL9/HLA-A2-restricted CD45RA+CD27− effector T cells express lower levels of CD28 compared to that of CD45RA−CD27+ memory T cells." (PMID 20844584, 2010). "Differences in the expression pattern of CD28 were also observed in the lung-resident influenza-specific CD8+ T cell subsets." (PMID 20844584, 2010). "The accumulation of CD28-effector T-cells has been shown to accompany an impaired response to influenza vaccination." (PMID 20716329, 2010).